LEP (leptin)
Diseases named in the same sentence as LEP in open-access papers (continued):
Sharing a sentence is not in itself a finding about the gene and the disease.
Obesity (continued). "Besides, neuroanatomic interactions can be impaired by obesity-related leptin resistance, which is involved in the genesis of OSA." (PMID 36241991, 2022). "Moreover, by producing leptin, obesity also impairs the function of T cells, increasing the proportion of exhausted PD-1 positive T cell." (PMID 35296087, 2022). "Overall, these results may suggest that modulation of the gut microbiota could be a novel therapeutic target to target leptin signaling during obesity and obesity-related complications, including CRC." (PMID 35563103, 2022). "Taken together, the results indicated that the protective effect of FAK on obesity may be related to the regulation of Leptin and IL-27." (PMID 36698478, 2022). "Serum obesity-related factors, including interleukin-6, leptin, and free fatty acid (FA), could further affect its circulating level." (PMID 36387855, 2022). "Leptin is produced primarily by adipocytes and is directly related to whole-body obesity." (PMID 35011721, 2022). "This supports findings that leptin might be involved in EC development via pathways beyond obesity-related pathophysiology, including through angiogenesis." (PMID 36505829, 2022). "Conclusively, these findings demonstrated that FAK intervention can effectively improve obesity in mice caused by HFD and the potential mechanisms was related to the regulation of serum levels of leptin and IL-27, lipogenesis and lipolysis in adipose tissue and gut microbiota composition." (PMID 36698478, 2022). "IL-17–leptin/adiponectin axis plays a key role in airway inflammation in obesity-related asthma." (PMID 36051916, 2022). "Both leptin and adiponectin are adipokines/hormones released primarily from adipose tissue, but the former is also produced in vascular smooth muscle cells and its concentration is elevated both in obesity and in CVDs, including hypertension." (PMID 35268057, 2022). "Moreover, if leptin plays a pro-inflammatory role during obesity, adiponectin exerts an anti-inflammatory action, and its decrease in obese patients exacerbates obesity-induced inflammation." (PMID 35624723, 2022). "The study demonstrated that HFD-induced obesity in rats had a substantial increase in serum leptin and declined adiponectin level, whereas the animal group treated with geraniol significantly improved the adiponectin level and lessened the serum leptin level." (PMID 36304965, 2022). "Leptin, an adipokine, is secreted from adipose tissue under the control of the obesity gene." (PMID 35031012, 2022). "Obesity has been correlated with higher levels of leptin, supporting the hypothesis that this hormone is mainly produced by white adipose-tissue cells." (PMID 36010052, 2022). "Although studies of the common obesity genetics were determined by genome-wide association studies (GWASs), this stage was set by research on monogenic obesity, which emphasized that the leptin–melanocortin signaling pathway is the major regulator of food intake." (PMID 35627568, 2022). "Leptin treatment reduces cardiac wall thickness and cardiomyocyte hypertrophy in leptin-deficient ob/ob mice independent of obesity, and protects cardiomyocytes from hypoxia-induced apoptosis, suggesting leptin exhibits cardioprotective effects against obesity and hypoxia." (PMID 36160851, 2022). "Moreover, we found that GLP-1 predicted obesity status and IR, even after controlling for BMI, whereas leptin predicted obesity and its markers, but after controlling for BMI, this association was annulled." (PMID 35334929, 2022). "Interestingly, our interaction analysis found that obesity status and sex had a significant interactive effect in LEP SNPs related to leptin levels in patients with IVDD." (PMID 36293132, 2022). "Leptin signals through the different leptin-receptor (LEP-R) isoforms, and loss of leptin as well as the leptin-receptor function, has been linked to extreme obesity, immune dysfunction and infertility." (PMID 36289764, 2022).
Obesity (continued). "Therefore, this study aimed to analyze associations between FTO (rs9939609), FABP2 (rs1799883), and LEP (rs2167270), LEPR (rs1137101), and MC4R (rs17782313) polymorphisms and obesity-related parameters." (PMID 35627568, 2022). "Regardless, the placenta remains normosensitive to insulin in women with obesity, thus, increased placental insulin activation, along with leptin, has been shown to promote mTOR signaling leading to increased glucose and amino acid transport across the placental barrier and fetal overgrowth." (PMID 36329895, 2022). "In our study cohort, pre-pubertal children with obesity and with low z-scores of circulating leptin levels are characterized by an altered metabolic profile including higher triglyceride, insulin and c-peptide concentrations compared to children with normal z-scores of circulating leptin levels." (PMID 35677722, 2022). "Leptin as a cross-link between obesity and OA, could offer new insights into the understanding of the mechanism by which weight loss improves OA symptoms." (PMID 35270000, 2022). "Research shows that leptin is a marker of obesity and reflects the degree of adiposity." (PMID 35721764, 2022). "Lack of sleep has been shown to alter the serum leptin and ghrelin levels, resulting in increased hunger and appetite, increased caloric intake and subsequent risk of obesity." (PMID 35041712, 2022). "In addition, several experts have highlighted that the bidirectional relationship between obesity and psoriasis starts from a pro-inflammatory state coupled with excessive adipokines secretion such as leptin, a phenomenon shared by these pathologies." (PMID 35886846, 2022). "Obesity in rats fed a HFD may be due to the higher caloric value of the diet as well as to increased concentrations of leptin and reduced concentrations of ghrelin, as noted in our study." (PMID 34550535, 2022). "Another common mediator of energy balance and mood symptoms might be leptin, as leptin and leptin receptors play roles in obesity." (PMID 36077028, 2022). "Obesity results in an elevated plasma level of leptin and resistance to this hormone." (PMID 35334918, 2022). "An imbalance of adiponectin and leptin in obesity leads to a low-grade inflammatory status." (PMID 36366375, 2022). "Customized gene panel spanning genes involved in the hypothalamic leptin-melanocortin system, their clinical significance in regard to obesity and other metabolic syndromes, and inheritance patterns such as autosomal dominant (AD), autosomal recessive (AR) and mitochondrial inheritance (Mu)." (PMID 35574020, 2022). "However, the study of the obesity epidemic has elucidated leptin resistance pathways, with too much leptin leading to infertility." (PMID 35760406, 2022). "Mice lacking ADCY3 exhibit obesity that is caused by a decrease in activity, hyperphagia, and leptin resistance." (PMID 36568981, 2022). "Leptin and its receptor are key factors in the development of obesity." (PMID 35782067, 2022). "Furthermore, we used only data from MCI participants without obesity to strengthen the homogeneity of the study sample by excluding the potential confounding effects of obesity on adiponectin or leptin levels and cognition." (PMID 36329496, 2022). "Long-term excessive fructose consumption leads to leptin resistance and, as a consequence, obesity." (PMID 36387906, 2022). "IR and leptin are increased in hypothyroid children and adolescents; more in those with obesity." (PMID 35501770, 2022). "Leptin, obesity, and TGFβ play a crucial role in the profibrogenic responses within the liver." (PMID 34663892, 2022). "Hyperleptinemia, preceding or indicating leptin resistance, may create a pro-inflammatory environment, all potentially leading to obesity, diabetes, and increased cardiovascular risks." (PMID 35629167, 2022).
Obesity (continued). "Leptin resistance – a blunted response to leptin signalling, a weakened effector arm of this neuroendocrine homeostatic feedback loop – has emerged as an important pathological change in the development of obesity." (PMID 36327900, 2022). "Possible reasons include that short sleep duration would lead to changes in body hormone levels (leptin, insulin, ghrelin, cortisol) related to obesity and metabolism, accompanied by increased sedentary time, excessive food intake, and other unhealthy lifestyles additionally." (PMID 36313785, 2022). "The adipogenic hormone leptin, which is increased in obesity, may affect ventilatory drive and airway obstruction." (PMID 35318438, 2022). "Oxidative stress-induced senescence in adipose tissue is linked to higher leptin, IL-6, and TNF-α production in the SASP, suggesting that adipocyte senescence may be causal in obesity-related chronic inflammation." (PMID 36726470, 2022). "Obesity-induced leptin resistance leads to abnormal leptin-mediated signaling pathways." (PMID 35529938, 2022). "Thus, for a population of young adults who show signs of overweight and obesity, leptin replacement therapy would probably be beneficial." (PMID 35886710, 2022). "Also, obesity‐related leptin level not only decreased IL‐10 production by CD4+ T cells, but also reduced the in vitro suppressive function of these lymphocytes from lean and obese AA patients." (PMID 35734271, 2022). "The only exception is rs7204609, rs3764261 and rs7799039 SNPs of FTO, CRPT and LEP genes, the negative effect sizes (β = -0.155, -0.125, -0.103Kg/m2) indicate BMI lowering, obesity protective effect of their minor allele." (PMID 36126070, 2022). "A mediator of remodeling that is increased in obesity is leptin." (PMID 35610699, 2022). "In accordance with previous studies in mice and rats, we were able to show here that, on the one hand, HFD feeding leads to the development of obesity, leptin and insulin resistance, as well as hyperlipidemia, while on the other hand, treatment with TEL can prevent these scenarios." (PMID 35431918, 2022). "Monitoring leptin levels in acute lymphoblastic leukemia (ALL) survivors could be helpful in controlling obesity." (PMID 35386254, 2022). "Adiponectin had an inverse correlation with obesity, whereas leptin had a direct correlation." (PMID 36381753, 2022). "This hormone, mainly produced by adipose tissue but present in maternal milk, acts as an essential nutrient during lactation for the programming of a lean phenotype, and we have demonstrated that leptin treatment during the suckling period protects against diet-induced obesity in adulthood." (PMID 35684076, 2022). "These obesity markers were also significantly correlated with serum leptin levels, which suggests that circulating leptin could mediate the regulatory effects of estrogen signaling on adipose tissue homeostasis." (PMID 36293132, 2022). "Leptin resistance and elevated leptin levels are common in obesity." (PMID 35162142, 2022). "Leptin, an adipocyte-derived hormone, is correlated with obesity and psoriasis severity." (PMID 36532050, 2022). "Thus, along with IL-6, resistin, and TNF-α, leptin acts as an indicator of obesity initiation and insulin resistance." (PMID 36248900, 2022). "Leptin is known as the satiety hormone and high circulating amounts are indicative of resistance to its action due to both lower sensitivity and genetic defect in its receptors, which leads to hyperphagia and consequently to obesity." (PMID 35951512, 2022). "When obesity occurs during pregnancy, leptin resistance occurs in the body." (PMID 36615730, 2022). "This suggests that once the mechanisms of the leptin–melanocortin system are unraveled, new therapeutic strategies to tackle both obesity and diabetes may be on the horizon." (PMID 35328759, 2022). "In contrast to leptin levels, adiponectin levels are reduced in obesity." (PMID 35769076, 2022).
Obesity (continued). "Individuals with obesity have higher circulating leptin levels and some may be leptin-resistant, similar to the more widely known insulin-resistant state." (PMID 35769076, 2022). "Metabolic factors related to obesity involving leptin and estrogens have protective effects on BMD." (PMID 35501835, 2022). "Our findings indicate that increased leptin levels in obesity may contribute to airway fibrosis and hyperresponsiveness and that the impact of leptin on asthma outcomes may depend on sex." (PMID 35610699, 2022). "Historically, GF mice have been shown to be resistant to obesity when placed on a high-fat diet and have lower levels of adiposity and leptin when compared to their conventionally raised counterparts who have an intact gut microbiota; however, several more recent studies do not support this notion." (PMID 36233056, 2022). "Furthermore, the data analysed suggest that obesity in midlife and the elevated leptin levels seen in the obese lead to leptin resistance in the brain, which also predisposes to AD." (PMID 35563589, 2022). "However, HFD can induce leptin resistance and lead to obesity resulting in increased blood leptin levels." (PMID 36698478, 2022). "Therefore, we measured the plasma levels of leptin in neonatal 7-day male mice from the control group versus the maternal obesity group using ELISA." (PMID 35327669, 2022). "Overall, leptin resistance is either an adaptive response or a pathological state, which marks the onset of impaired leptin signalling under conditions of leptin excess, such as during obesity." (PMID 36855701, 2022). "This might be explained by the decreased ghrelin and increased leptin levels accompanied by low BMI in contrast to the results reported in obesity." (PMID 35334972, 2022). "It plays a role in lipodystrophy, obesity, and diabetes and can downregulate LEP gene expression." (PMID 35395810, 2022). "For research scientists, there are now numerous molecular targets for antiobesity drugs: central receptors for biogenic amines, cannabinoids, hypothalamic neuropeptides, peripheral β3-adrenoceptor, and UCPs; and dominating all obesity research is leptin—a tantalizing but frustrating obesity target." (PMID 35388304, 2022). "Besides, more experimental data are required to validate the effects of leptin on dendritic cells and mast cells in obesity-related asthma." (PMID 36551211, 2022). "Reports showed that leptin and insulin resistance play a vital role in the development of obesity." (PMID 36359937, 2022). "Many obesity-related genes are involved in the regulation of leptin-melanocortin pathway." (PMID 33826123, 2022). "The NEAT1-hsa-miR-204-5p-IGF1 axis may serve as a target for estradiol-leptin synergy in the uterine tissue of patients with obesity and as a biomarker to predict disease." (PMID 36362969, 2022). "Therefore, hyperleptinemia and leptin resistance are two major features of obesity likely to drive the detrimental effects of energy surplus on ovarian function." (PMID 36855701, 2022). "The present study was aimed at examining the involvement of different peripheral obesity-related biomarkers (namely, ghrelin, IR, and leptin/adiponectin ratio) to explain different eating styles, i.e., external, emotional, and restrained patterns, in childhood and adolescence obesity." (PMID 35057485, 2022). "The following factors have been reported to play a vital role in the carcinogenesis and progression of EORC: obesity-induced insulin resistance, chronic inflammation, microbiota, altered levels of adipokines, cytokines, various growth factors, adiponectin, and leptin." (PMID 35368890, 2022). "This discovery provided hope that regulating leptin synthesis might be possible to stem the tide of the increasing prevalence of overweight individuals and obesity." (PMID 35662925, 2022).
Obesity (continued). "Interestingly, obesity‐related leptin concentration significantly increased the ability of purified CD4+ T cells from lean AA patients to produce IL‐5, IL‐13, IL‐17 and IL‐6, but diminished IL‐10 release." (PMID 35734271, 2022). "Therefore, the serum levels of leptin and adiponectin can be considered representative parameters of the obesity state." (PMID 35990844, 2022). "In part because obesity triggers a state of leptin resistance." (PMID 36213285, 2022). "expressed leptin untethered to obesity and demonstrated that leptin overexpression during the weaning period (corresponding to the third trimester in human brain development) caused the mice to be overly suspectable to obesity when subsequently presented a highly palatable diet." (PMID 36329895, 2022). "However, in the context of obesity (with high leptin levels), the neuroendocrine effects of leptin on the reproductive axis often remain intact." (PMID 36394061, 2022). "Additionally, a partial reduction in plasma leptin levels can restore hypothalamic leptin sensitivity and effectively decrease weight gain as well as improve insulin sensitivity in obesity." (PMID 35355566, 2022). "The potential underlying mechanism by which obesity modulates the response to ICI therapy may involve obesity-induced immune aging and PD-1-mediated T cell dysfunction by leptin." (PMID 35493526, 2022). "This suggests that preterm infants can enterally absorb leptin from human milk, and leptin-rich breast milk may be a targeted therapy for the prevention of obesity." (PMID 36558383, 2022). "Thirdly, given that children’s obesity is homogeneous in this study, the hypothesized model was referenced to a model of an established adiposity-IR marker (leptin:adiponectin ratio)." (PMID 35370951, 2022). "Moreover, when the body is suffering from metabolic abnormalities, such as obesity, SOCS3 is involved in the inhibition of inflammatory cytokines and crucial hormones linked to energy metabolism, such as insulin signaling and leptin." (PMID 36145200, 2022). "In this regard, obesity (increased body fat mass) results in the production of pathologically high levels of circulating leptin and central leptin resistance, while being underweight (decreased body fat mass) results in the production of low levels of circulating leptin." (PMID 35527735, 2022). "The compound heterozygous carriers of pathogenic genetic variants in the autosomal recessive genes LEP, LEPR, POMC and PCSK1 are rare, obesity-associated variants in the autosomal dominant gene MC4R are the most common, with 0.8% of participants in our study carrying a variant in MC4R." (PMID 35574020, 2022). "Taking into account that obesity is significantly more frequent in diabetics, obesity, through leptin levels, could be another biological mechanism linking diabetes and the outcome of RCT." (PMID 35216099, 2022). "Genetics play an important role in inducing obesity and leptin resistance." (PMID 35628271, 2022). "For instance, several DEMs in the present work, including miR-144-5p, miR-192, miR-320, miR-378, miR-122, miR-24-3p, miR-223-3p and miR-146-5p, have been found to have strong correlations with various obesity-related metabolic indices in blood, such as serum leptin and triglycerides." (PMID 35798800, 2022). "Increasing levels of leptin can down-regulate the adipose mass while leptin resistance may occur in obesity individuals." (PMID 35173531, 2022). "Characterized by elevated serum leptin levels and decreased leptin sensitivity, leptin resistance is not completely understood but may represent a fundamental pathology of obesity." (PMID 35031012, 2022). "Of interest, the level of chemerin protein expression in WAT of obese animal models was observed to go down after injection of 0.5 μg/g leptin, demonstrating that leptin resistance may be one of the reasons for elevated chemerin protein expression in obesity." (PMID 35317838, 2022).